TCEANC2 (transcription elongation factor A N-terminal and central domain containing 2)
Synonyms: C1orf83; FLJ32112
Tractability: PROTAC: ubiquitination databases record sites on it.
Gene: Protein-coding gene on chromosome 1 (54,052,867 to 54,112,519, forward strand). Ensembl gene ENSG00000116205.
Subcellular location: Nucleus
Subcellular location (Human Protein Atlas): Nucleoplasm; Vesicles
Gene Ontology:
Molecular function: protein binding; transcription elongation factor activity
Biological process: transcription elongation by RNA polymerase II; DNA-templated transcription
Cellular component: nucleus
Genetic constraint (gnomAD): Loss-of-function variants: 18 observed, 21.04 expected, observed/expected ratio (o/e) 0.86, 90% interval 0.59 to 1.27. The upper end of that interval is the gene's LOEUF score, 1.27, which puts it in group 5 of 6, group 1 being the genes least tolerant of losing a copy. Missense variants: 250 observed, 257.3 expected, observed/expected ratio (o/e) 0.97, 90% interval 0.88 to 1.08. Synonymous variants: 84 observed, 98.65 expected, observed/expected ratio (o/e) 0.85, 90% interval 0.71 to 1.02.
Homologues: Orthologues: chimpanzee TCEANC2 (99% identical), macaque TCEANC2 (97% identical), rabbit TCEANC2 (92% identical), mouse Tceanc2 (91% identical), pig TCEANC2 (91% identical), dog TCEANC2 (90% identical), guinea pig TCEANC2 (88% identical), rat Tceanc2 (88% identical), zebrafish tceanc2 (65% identical).
Diseases named in the same sentence as TCEANC2 in open-access papers:
TCEANC2 is named in the same sentence as 2 diseases in open-access papers, as found by Europe PMC text mining. Sharing a sentence is not in itself a finding about the gene and the disease.
TCEANC2 shares sentences with these, for which no sentence is quoted: hypothyroidism (1 paper); prostate carcinoma (1).